TIMP1 (TIMP metallopeptidase inhibitor 1)
Diseases named in the same sentence as TIMP1 in open-access papers (continued):
Sharing a sentence is not in itself a finding about the gene and the disease.
COVID-19 (23 papers, 2021 to 2025). A disease caused by infection with severe acute respiratory syndrome coronavirus 2. "The respective APNet bipartite graph contained a large cluster (IL10RA, ACTN4, ITGB2, IL2RB, BIRC2, ITGAM, HMOX1, TIMP1) linked with established COVID-19 inflammatory and immune signalling cascades." (PMID 39921901, 2025). "pointed out that in patients with COVID-19, circulating TIMP-1 was associated with disease severity and systemic inflammatory index." (PMID 37063869, 2023). "At first, we demonstrated that MMP-2, MMP-9, and TIMP-1 were elevated among COVID-19 patients and associated with COVID-19 severity, which is consistent with altered extracellular matrix remodelling." (PMID 37509076, 2023). "Interestingly, many pro-inflammatory genes including S100A8 and S100A9, chemotaxis genes such as CXCR2 and FPR1, and NETosis-associated genes such as TIMP1 were highly expressed in neutrophils of ANPEP-high patients with COVID-19 compared with ANPEP-low patients with COVID-19." (PMID 40168094, 2025). "TIMP-1 was downregulated in convalescent patients recovering from mild Omicron cases, supporting previous findings of TIMP-1’s correlation with COVID-19 severity." (PMID 40557167, 2025). "In line with all these authors, we observed higher plasma levels of MMP-9 and TIMP-1 in COVID-19 patients who developed ARDS." (PMID 37509076, 2023). "A larger sample size was needed to obtain a better assessment of TIMP-1 circulating levels as a prognostic biomarker in COVID-19 patients and to investigate its potential role in monitoring post-COVID symptoms." (PMID 37509076, 2023). "Using next-generation ELISA, the plasma levels of MMP-9 and TIMP-1 were evaluated in 129 COVID-19 patients and 53 HD." (PMID 37509076, 2023). "RPS29, S100A10, and TIMP1 were the critical genes in the brain pathology of COVID-19 in elderly patients." (PMID 37063869, 2023). "TIMP-1 and MMPs are worthy of further studies to assess their potential as prognostic and predictive biomarkers in COVID-19 patients." (PMID 37509076, 2023). "To further explore the expression and role of TIMP1, we found that the expression of TIMP1 was significantly elevated in the brains of COVID-19 patients by scatter plots." (PMID 37063869, 2023). "Significantly increased levels of the metalloproteinase inhibitor tissue inhibitor of metalloproteinases 1 (TIMP-1) and of TIMP-1 in complex with MMP-9 were found in COVID-19 BAL fluids compared with influenza BAL fluids." (PMID 34793331, 2022). "We also observed an increase in macrophages and the transcript expression of MMP-1, -2, -14- and 24, as well as TIMP-1 and -2 in the lungs of human COVID-19 patients." (PMID 35512020, 2022). "BAL fluid levels of TIMP-1/MMP-9 complexes were significantly elevated in COVID-19 patients having a bacterial-fungal coinfection compared with COVID-19 patients having a bacterial coinfection." (PMID 34793331, 2022). "Plasma TIMP-1 concentrations were higher in subjects with severe COVID-19 than controls (p=0.0032)." (PMID 38956476, 2024). "Finally, an investigation of neuronal (NfL) and astrocyte damage (GFAP), myeloid activation (sCD163) and BBB permeability (MMP-9 and TIMP-1) was performed on the CSF samples of hospitalized COVID-19 patients with severe NS on hospital admission." (PMID 37759493, 2023). "We speculated that the stimulation of the fibrotic process, the inhibition of proteolysis, and the promotion of proinflammatory processes by TIMP-1 could worsen the outcome of COVID-19." (PMID 37509076, 2023). "Timp1-targeted siRNA was shown to prevent inflammatory and destructive changes in the lungs in an LPS-induced ALI model in mice, which is highly relevant to COVID-19-associated ARDS in humans." (PMID 36675165, 2023). "This study aimed to investigate MMP-9 and TIMP-1 levels in patients diagnosed with COVID-19 and whether the MMP-9/TIMP-1 ratio is associated with lung involvement in COVID-19." (PMID 37545954, 2023).
COVID-19 (continued). "In this study, we found a marked increase in TIMP1 expression in the brain of COVID-19 patients." (PMID 37063869, 2023). "In addition, in patients with severe COVID-19, increased concentrations of neutrophil elastase, gelatinolytic activity, and TIMP-1/MMP-9 complexes were found." (PMID 34829883, 2021). "In addition, other factors like the immunomodulatory calcium binding protein S100A9 as well as the tissue inhibitor of metalloproteinases-1 (TIMP-1), both of which were described to correlate with poor prognosis in COVID-19 patients, were also significantly decreased by treatment with mFas-Fc." (PMID 38514848, 2024). "The serum levels of MCP-1, TIMP-1, I-309, TNF-RI and TNF-RII were increased, while that of eotaxin-2 was decreased in COVID-19 patients." (PMID 38726341, 2024). "Finally, among the 15 COVID-19 patients with severe NS on hospital admission requiring PL for diagnostic purposes, an investigation of neuronal and astrocyte damage (NfL and GFAP), myeloid activation (sCD163) and BBB alteration biomarkers (MMP-9 and TIMP-1) on CSF samples was performed." (PMID 37759493, 2023). "Herein, we investigated the plasma levels of MMP-9, TIMP-1 as well as the plasma activity of MMP-2 and MMP-9 in a cohort of well-characterized patients with COVID-19 at an acute stage of the disease and after three months from hospital discharge." (PMID 37509076, 2023). "On hospital admission, COVID-19 patients showed significantly higher plasma levels of MMP-9 and TIMP-1 as well as a higher MMP-9/TIMP-1 ratio compared to HD (p < 0.0001, p < 0.0001 and p = 0.0299, respectively) (respectively)." (PMID 37509076, 2023). "This was also highlighted by the positive correlation between plasma TIMP-1 and the chest CT score, highlighting the potential role of TIMP-1 in the fibrotic process during COVID-19." (PMID 37509076, 2023). "Recently, CypA and TIMP1 have been suggested as potential treatments for SARS-CoV-2 infection and COVID-19." (PMID 35563714, 2022). "Interestingly, TIMP-1 is the most related differential gene between RPS29 and S100A10, these results demonstrate the presence of intracranial inflammatory response in COVID-19 patients." (PMID 37063869, 2023). "Our study is the first to investigate the relationship between COVID-19 and MMP-9 and TIMP-1." (PMID 37545954, 2023). "Further WGCNA analysis suggested that ribosomal dysfunction may play a key role in brain dysfunction in elderly COVID-19 patients, with RPS29, S100A10, and TIMP1 as key molecules." (PMID 37063869, 2023). "In conclusion, we show hyperinflammation characterized by significantly increased cytokine and chemokine levels, hyperactivated neutrophils, and elevated levels of protease inhibitors TIMP-1, SLPI, and elafin in the lungs of critically ill COVID-19 patients in comparison with influenza patients." (PMID 34793331, 2022). "In CD14+ monocytes, HIF-1 signaling may regulate LDHA, ALDOA, TIMP1, ELOB and IFNGR2, and PPAR signaling may regulate UBC, RXRA, DBI and ACSL1 in COVID-19 patients." (PMID 33936072, 2021). "Based on the expression of TIMP1, further analysis by GSEA revealed that the pentose and glucuronate interconversions pathways were significantly enriched in the TIMP1 low expression group, indicating that the metabolic pathways in the brain of COVID-19 patients were disrupted." (PMID 37063869, 2023). "There is no COVID-19 study related to TIMP-1 in the literature." (PMID 37545954, 2023). "Consistently, proteomic and metabolomics data from CMs revealed several genes (KNG1, TXNIP, ITIH4, TIMP1, SERPING1/2/3, ITGA1, ADAR, and CLIC5 etc.)and molecules (adenosine and inosine) were related with platelet activation, thus, adding antiplatelet might be a possible therapeutic for COVID-19." (PMID 35903092, 2022).
COVID-19 (continued). "Additionally, 13 of 55 angiogenic proteins including TIMP-1, uPA, VEGF, MMP-8/9, CXCL4/16, Endoglin, Angiogenin or Angiopoietin-2 were uniquely downregulated in 3-months post-COVID-19 patients without PE compared to those who suffered a PE." (PMID 38324145, 2024).
emphysema (23 papers, 2010 to 2025). "Elevated levels of matrix metalloproteinase-9 (MMP-9) and an increased MMP-9/TIMP-1 ratio are consistently associated with emphysema severity and extracellular matrix degradation in COPD." (PMID 41373549, 2025). "In the cohort of 101 emphysema subjects correlative analyses were done to determine if MMP or TIMP-1 levels were associated with key disease parameters or change in lung function over an 18-month time period." (PMID 23441181, 2013). "These mediators are implicated in emphysema, and we demonstrate that treatment with IL-6 neutralizing antibodies is associated with decreased expression of MMPs and TIMP-1." (PMID 21799929, 2011). "In the same way, the inability of betamethasone to rebalance MMP-2-9/TIMP-1-2 ratio has been related to its inability to prevent the development of pulmonary emphysema associated to cadmium inhalation for 5 weeks and a similar mechanism has been described in dogs." (PMID 25313925, 2014). "Thus, our data indicating an increase in MMP-9: TIMP-1 ratio in vitamin D deficient smoke-exposed mice provides a mechanism whereby vitamin D deficiency can influence and accelerate the development of emphysema." (PMID 23781205, 2013). "When the upregulating MMP-9 cannot be offset by TIMP-1 abundantly, the degradation of elastin and other extracellular matrix components occurs in the alveolar walls and finally leading to emphysema." (PMID 35936787, 2022). "The MMP-9 concentration and the MMP-9/TIMP-1 ratio were higher in patients with emphysema than in those with other phenotypes." (PMID 33419373, 2020). "This and other studies have suggested that the MMP-9 concentration and the MMP-9/TIMP-1 ratio are the best predictors of emphysema in COPD patients." (PMID 33419373, 2020). "Serum levels of MMPs -1, -2, -7, -9, and TIMP-1 have been reported to be elevated in emphysema subjects and correlate with the GOLD stages." (PMID 32878618, 2020). "In our study, MMP-9 concentration and the MMP-9/TIMP-1 ratio were the best predictors of emphysema in COPD patients." (PMID 30781876, 2019). "MMP-9 concentration and the MMP-9/TIMP-1 ratio were the best predictors of emphysema in COPD patients." (PMID 30781876, 2019). "MMP-9 concentrations and the MMP-9/TIMP-1 ratio were higher in patients with emphysema than in other phenotypes (both p < 0.01)." (PMID 30781876, 2019). "MMP-9 concentration and the MMP-9/TIMP-1 ratio were higher in patients with emphysema than in other phenotypes (both with p < 0.01)." (PMID 30781876, 2019). "MMP-9 concentration and the MMP-9/TIMP-1 ratio were higher in patients with emphysema than in other phenotypes, and FEV1 was correlated with MMP-9/TIMP-1 imbalance." (PMID 30781876, 2019). "MMP-9 concentration and the MMP-9/TIMP-1 ratio are the best predictors of emphysema in COPD patients." (PMID 30781876, 2019). "TIMP-3 null mice develop emphysema while human studies show TIMP-1 and -2 are raised in the airways of COPD subjects and TIMP-2 polymorphisms are associated with CLE." (PMID 27460105, 2016). "In contrast to BALF, plasma MMP-9 and TIMP-1 levels were actually decreased in the emphysema cohort compared to the control groups." (PMID 23441181, 2013). "BALF TIMP-1 levels were higher in smokers and emphysema subjects compared to controls and those with emphysema had even higher levels than active smokers." (PMID 23441181, 2013). "This was despite the fact that TIMP-1 levels were much higher in the emphysema cohort than the active smokers." (PMID 23441181, 2013). "The decrease in plasma MMP-9 and TIMP-1 levels that were measured in the emphysema cohort contrasted with a recent study that showed that serum levels of these proteins were elevated in COPD." (PMID 23441181, 2013). "An imbalanced MMP-9/TIMP-1 ratio is an important determinant in the pathogenesis of emphysema." (PMID 38790616, 2024). "FEV1 was correlated with MMP-9/TIMP-1 imbalance in patients with emphysema (r = 0.664, p < 0.001)." (PMID 30781876, 2019).
emphysema (continued). "Gal-9 significantly reduced MMP-9, MMP-2 and TIMP-1 levels in BALF on day 7 in the emphysema model." (PMID 28704475, 2017). "Moreover, this increase in activity occurred despite the fact that TIMP-1 levels were notably higher in the emphysema cohort compared to the smoking group." (PMID 23441181, 2013). "Furthermore, TIMP-1 preferentially inhibits MMP-9, a key metalloproteinase in the pathogenesis of emphysema; therefore, TIMP-1 may exert protection, while the levels of MMP-9 and the MMP-9/TIMP-1 ratio are reliable predictors of emphysema." (PMID 36835197, 2023). "Human MMP-9 was shown to induce emphysema in a murine model, and MMP-9/TIMP-1 imbalance was observed in patients with COPD." (PMID 33992109, 2021). "Human MMP-9 induced emphysema in a murine model, and an MMP-9/TIMP-1 imbalance was observed in COPD patients with exacerbations." (PMID 30606200, 2019). "In the present study, exogenous administration of Gal-9 in an emphysema animal model reduced the levels of MMP-9, MMP-2 and TIMP-1 in BALF, and these MMPs levels correlated significantly with the number of neutrophils in BALF." (PMID 28704475, 2017). "Despite the high TIMP-1 levels, elastase and collagenase activity were significantly increased within the BALF of the emphysema cohort." (PMID 23441181, 2013). "BALF TIMP-1 levels were also altered amongst the three study cohorts (TIMP-1 4.2±7.2 ng/ml in control, 11.5±11.8 ng/ml in smokers, 127.8±189.7 in emphysema; p<0.0001 by Kruskal-Wallis test)." (PMID 23441181, 2013). "In fact, in the emphysema cohort, those with high MMP levels frequently had very low levels of TIMP-1 indicating that a proteolytic imbalance is likely present within the lung of the emphysema subjects." (PMID 23441181, 2013). "Both in the BALF and plasma, MMP and TIMP-1 measurements in the emphysema subjects did not correlate with important disease parameters and were not predictive of subsequent functional decline." (PMID 23441181, 2013). "Compared to non-smoking controls, MMP and TIMP-1 BALF levels were significantly elevated in the emphysema cohort." (PMID 23441181, 2013). "CS-induced pulmonary inflammation, peribronchial lymphoid aggregates, increase in MMP-12/TIMP-1 mRNA ratio, emphysema and failure to gain weight were not significantly different in Ptx3 KO mice compared to WT mice." (PMID 20920344, 2010). "Among smokers without COPD, the activities of MMP-9 and TIMP-1 result in recovery and resolution, whereas for smokers with COPD, this results in ECM destruction and emphysema." (PMID 30781876, 2019).
endometriosis (23 papers, 2006 to 2025). The growth of functional endometrial tissue in anatomic sites outside the uterine body. "Remarkably, although MMPs regulate the pathophysiology and development of endometriosis, TIMP-1 and -2 expression levels are decreased in this condition." (PMID 40565017, 2025). "MMP7, MMP9, MMP11, and TIMP1 were observed to be significantly upregulated in women with adenomyosis as compared to endometriosis." (PMID 41272701, 2025). "Out of these, significant overexpression of MMP7, MMP9, MMP11, IGFBP5, and TIMP1 was observed at both gene and protein levels in adenomyosis as compared to endometriosis." (PMID 41272701, 2025). "TIMP-1 showed inconsistent regulation between different biological compartments in women with endometriosis, with reported decreases in blood and ovarian tissue and an increase in peritoneal fluid across well-powered cohorts." (PMID 38341605, 2024). "The validation results showed increased levels of miR-106b-3p, miR-451a, miR-486-5p, IL-6, IL-8, urokinase plasminogen activator (uPA), and tissue inhibitor of metalloproteinases type 1 (TIMP-1) in the peritoneal fluid from patients with endometriosis." (PMID 37834449, 2023). "In the present study, the patients with endometriosis showed higher levels of TIMP1 and MMP2 in the peritoneal fluid, as compared to the controls." (PMID 34686725, 2021). "High levels of MMP-2 and MMP-9 and low levels of TIMP-1 were related with low production of mature oocytes and subsequent decreased quality of embryos in endometriosis patients who underwent in vitro fertilization (IVF)." (PMID 31037923, 2019). "Previous data reported that an excessive TIMP1 secretion in endometriosis was deleterious to ovulation and embryo development." (PMID 28174513, 2017). "TIMP1 exhibited upregulation in adenomyosis as compared to controls as well as endometriosis." (PMID 41272701, 2025). "In patients with endometriosis, the higher expression of TIMP-1 during ovulatory phase might contribute in inhibiting the proteolitic activity and the liquefaction of CM, which is essential for CM permeability to spermatozoa." (PMID 28174513, 2017). "These genes may promote the infiltration and metastasis of tumor cells in the tumor microenvironment by affecting intercellular adhesion and matrix degradation, similarly in recent years studies have shown that TIMP1 is highly expressed in endometrial cancer and endometriosis tissues." (PMID 39650066, 2024). "In order to clarify the role of metalloproteases and their inhibitors in endometriosis development, MMP2, MMP3, MMP10, TIMP1, and TIMP2 expression was measured in healthy and eutopic endometrium, in OMA and DIE lesions." (PMID 32325785, 2020). "Since endometriosis creates a corner an increase in PAI-1 and TIMP-1 is detected, resulting in the cessation of further proteolytic activity." (PMID 24294950, 2013). "The expression of VEGF-A, IL-8, and TIMP-1 was increased in the peritoneal fluid of infertile and fertile endometriosis patients compared to fertile patients without endometriosis." (PMID 37834449, 2023). "According to our review of the literature here, COMP, AGT, TGFBI and ANGP4 have not yet been associated with endometriosis, while S100A8, C163A, EGFR and TIMP1 have." (PMID 34686725, 2021). "Recent studies reported that matrix metalloproteinase-2 (MMP-2), MMP-9, tissue inhibitor of matrix metalloproteinases (TIMP-1) and transforming growth factor-β2 (TGF-β2) express a tendency to higher gene expression in the eutopic endometrium of women with endometriosis." (PMID 28174513, 2017).
endometriosis (continued). "The expressions of TIMP-1, -2, and -3 were reported to be significantly lower in endometriotic tissues than normal eutopic endometrium, and an experimental study showed that the addition of TIMP protein to the peritoneal cavity of nude mice prevented the establishment of endometriosis." (PMID 36752987, 2023).